CYP2C19 (cytochrome P450 family 2 subfamily C member 19)
Description:
A cytochrome P450 monooxygenase involved in the metabolism of polyunsaturated fatty acids (PUFA). Mechanistically, uses molecular oxygen inserting one oxygen atom into a substrate, and reducing the second into a water molecule, with two electrons provided by NADPH via cytochrome P450 reductase (NADPH--hemoprotein reductase). Catalyzes the hydroxylation of carbon-hydrogen bonds. Hydroxylates PUFA specifically at the omega-1 position. Catalyzes the epoxidation of double bonds of PUFA. Also metabolizes plant monoterpenes such as limonene. Oxygenates (R)- and (S)-limonene to produce carveol and perillyl alcohol. Responsible for the metabolism of a number of therapeutic agents such as the anticonvulsant drug S-mephenytoin, omeprazole, proguanil, certain barbiturates, diazepam, propranolol, citalopram and imipramine. Hydroxylates fenbendazole at the 4' position.
Synonyms: P450IIC19; CPCJ; CYP2C; CYPIIC17; CYPIIC19; P450C2C
Tractability: Small molecule: a structure with a bound ligand is known; a high-quality ligand is known; it belongs to a druggable protein family. Antibody: its Gene Ontology location is reachable by antibodies, with high confidence; UniProt places it where antibodies can reach, with medium confidence. PROTAC: a small molecule that binds it is known.
Target class: Cytochrome P450; Cytochrome P450 family 2; Enzyme; Cytochrome P450 family 2C; Cytochrome P450 2C19
Safety:
Unwanted effects reported when the protein is acted on. In parentheses: how it was acted on, where the effect was seen, and who reports it.
adverse cardiac and cerebrovascular events (source: ClinPGx)
agitation and dysphoria (source: ClinPGx)
becoming overweight (source: ClinPGx)
bleeding (source: ClinPGx)
bleeding events (source: ClinPGx)
drug reaction with eosinophilia and systemic symptoms (DRESS) (source: ClinPGx)
drug toxicity (source: ClinPGx)
hemorrhage (source: ClinPGx)
hypertension (source: ClinPGx)
leukopenia (source: ClinPGx)
maculopapular exanthema (source: ClinPGx)
neutropenia (source: ClinPGx)
not studied (source: ClinPGx)
over-anticoagulation (source: ClinPGx)
side effects or intolerance (source: ClinPGx)
Gene: Protein-coding gene on chromosome 10 (94,762,662 to 94,856,282, forward strand). Ensembl gene ENSG00000165841.
Subcellular location: Endoplasmic reticulum membrane; Microsome membrane
Subcellular location (Human Protein Atlas): Vesicles
Pathways (Reactome):
Metabolism: CYP2E1 reactions; Synthesis of (16-20)-hydroxyeicosatetraenoic acids (HETE); Synthesis of epoxy (EET) and dihydroxyeicosatrienoic acids (DHET); Xenobiotics
Drug ADME: Aspirin ADME
Gene Ontology:
Molecular function: (R)-limonene 6-monooxygenase activity; (S)-limonene 6-monooxygenase activity; (S)-limonene 7-monooxygenase activity; enzyme binding; heme binding; long-chain fatty acid omega-1 hydroxylase activity; monooxygenase activity; oxidoreductase activity; oxidoreductase activity, acting on paired donors, with incorporation or reduction of molecular oxygen, reduced flavin or flavoprotein as one donor, and incorporation of one atom of oxygen; steroid hydroxylase activity; oxygen binding; arachidonate 11,12-epoxygenase activity; arachidonate 14,15-epoxygenase activity; arachidonate 8,9-epoxygenase activity; fatty acid omega-1 hydroxylase activity; iron ion binding; oxidoreductase activity, acting on paired donors, with incorporation or reduction of molecular oxygen
Biological process: long-chain fatty acid metabolic process; monoterpenoid metabolic process; steroid metabolic process; xenobiotic catabolic process; xenobiotic metabolic process; epoxygenase P450 pathway; omega-hydroxylase P450 pathway; fatty acid metabolic process; monocarboxylic acid metabolic process; terpenoid metabolic process
Cellular component: cytoplasm; endoplasmic reticulum membrane; intracellular membrane-bounded organelle
Genetic constraint (gnomAD): Loss-of-function variants: 51 observed, 38.55 expected, observed/expected ratio (o/e) 1.32, 90% interval 1.06 to 1.67. The upper end of that interval is the gene's LOEUF score, 1.67, which puts it in group 6 of 6, group 1 being the genes least tolerant of losing a copy. Missense variants: 713 observed, 564.45 expected, observed/expected ratio (o/e) 1.26, 90% interval 1.19 to 1.34. Synonymous variants: 242 observed, 199.23 expected, observed/expected ratio (o/e) 1.21, 90% interval 1.09 to 1.35.
Homologues: Orthologues: chimpanzee CYP2C19 (89% identical). Paralogues in human: CYP2C9 (91% identical), CYP2C18 (81% identical), CYP2C8 (78% identical), CYP2E1 (58% identical), CYP2A13 (51% identical), CYP2A6 (51% identical), CYP2F1 (50% identical), CYP2A7 (50% identical), CYP2B6 (48% identical), CYP2S1 (44% identical), CYP2D6 (41% identical), CYP2J2 (40% identical), and 3 more.
Diseases named in the same sentence as CYP2C19 in open-access papers:
CYP2C19 is named in the same sentence as 249 diseases in open-access papers, as found by Europe PMC text mining. Sharing a sentence is not in itself a finding about the gene and the disease. The quoted sentences say what the papers report.
Stroke (83 papers, 2010 to 2026). Sudden impairment of blood flow to a part of the brain due to occlusion or rupture of an artery to the brain. "A study published in the Journal of the American Medical Association reported that carriers of the CYP2C19 loss-of-function allele face higher risks of cardiovascular death, myocardial infarction, and stroke, particularly for in-stent thrombosis events." (PMID 40552191, 2025). "The CHANCE-2 trial results demonstrated that among Chinese patients with minor ischemic stroke or transient ischemic attack (TIA) carrying CYP2C19 LoF alleles, ticagrelor was associated with a modestly reduced risk of stroke at 90 days compared to clopidogrel." (PMID 40422573, 2025). "Current consensus suggests that clopidogrel exhibits a limited secondary prevention effect on stroke in carriers of CYP2C19 loss-of-function alleles." (PMID 40248010, 2025). "Two meta-analyses of clopidogrel-treated patients revealed that CYP2C19 LOF allele carriers were more likely to experience stroke and other combined vascular events than were noncarriers." (PMID 40640196, 2025). "Another study has also shown that CYP2C19*2 and *3 variant alleles significantly increase the risk of stroke in CI patients taking clopidogrel antiplatelet during cerebrovascular angiography (DSA) and stent implantation." (PMID 39472784, 2024). "Results demonstrated a decreased risk of stroke at 90 days with ticagrelor compared to clopidogrel in patients with the CYP2C19 loss-of-function mutation." (PMID 38361699, 2024). "The associations between the CYP2C19 genotype distribution and three different types of stroke were also investigated in this work." (PMID 38671468, 2024). "Recent draft guidance from the National Institute for Health and Care Excellence (NICE) recommends CYP2C19 genotype testing for people at risk of a secondary stroke." (PMID 38490995, 2024). "There is convincing evidence of an association between CYP2C19 genotype and clinical outcomes in stroke or TIA patients treated with clopidogrel." (PMID 38038819, 2024). "Randomized clinical trials have shown that aspirin-ticagrelor was associated with a lower risk of stroke at 90 days among patients with TIA or minor ischemic stroke who carried the CYP2C19 loss-of-function allele." (PMID 37638175, 2023). "The recent CHANCE-2 trial in China showed that among patients with TIA or minor ischemic stroke who were carriers of CYP2C19 loss-of-function alleles, the risk of stroke at 90 days in the ticagrelor group was modestly lower than that in the clopidogrel group." (PMID 37638175, 2023). "In East Asians presenting with AMI, CYP2C19 PM was associated with deleterious cardiovascular outcomes and stroke." (PMID 36072879, 2022). "No previous studies have demonstrated the association between DNA methylation of CYP2C19 and MACEs, such as recurrent angina, MI, stroke, or death." (PMID 36843628, 2022). "The Ticagrelor vs. Clopidogrel in CYP2C19 Loss-of-Function Carriers with Stroke or TIA (CHANCE-2) trial was a multicenter, double-blinded, placebo-controlled, randomized control, superiority trial conducted across 202 centers in China." (PMID 36082121, 2022). "As regards cerebrovascular disease, a meta‐analysis reported a relationship between CYP2C19 poor metaboliser alleles and efficacy of clopidogrel in secondary prevention of stroke/TIA." (PMID 35001413, 2022). "CYP2C19 LoF carriers had significantly increased risk of strokes (HR 1.63, 95% CI 1.01 to 2.64, p=0.047) in this period." (PMID 34903548, 2021). "Clinical relevance of CYP2C19*2 has been described as well as association with risk of cardiovascular events, stroke and major bleeding." (PMID 34065778, 2021). "We illustrate these approaches by re-analysing primary-care-linked UK Biobank data relating to CYP2C19 genetic variants, Clopidogrel use and stroke risk, and data relating to APOE genetic variants, statin use and Coronary Artery Disease (CAD)." (PMID 34495953, 2021).
Stroke (continued). "This study sought to assess the cost-effectiveness of CYP2C19 genotyping to guide drug therapy for acute minor strokes or high-risk TIAs in China." (PMID 33795788, 2021). "We illustrate these approaches by re-analysing primary-care-linked UK Biobank data relating to CYP2C19 genetic variants, Clopidogrel use and stroke risk, and data relating to APOE genetic variants, statin use and Coronary Artery Disease." (PMID 34495953, 2021). "The association between CYP2C19 LoF carrier status and stroke or MI was consistent (although attenuated due reduced sample sizes in subgroups) in participants who received an aspirin prescription (n=3730." (PMID 34903548, 2021). "To conclude, intermediate and low metabolisers (due to CYP2C19 LOF alleles) who were prescribed clopidogrel in the primary care setting had substantially increased risks of incident hospital-diagnosed strokes and MIs, compared with normal metabolisers." (PMID 34903548, 2021). "Kidney dysfunction alters the association between CYP2C19 variants and clopidogrel effects in patients with stroke or transient ischemic attack." (PMID 32357528, 2020). "The importance of pharmacogenomic guidance is shown by a systematic review of five studies (total n = 2900 patients, average age 67 years) of the effects of CYP2C19 variants on the outcomes of myocardial infarcts, revascularisation, stroke or death." (PMID 32796505, 2020). "A study of 2933 Chinese patients with a transient ischemic attack or minor stroke found that the 42% who had loss-of-function variants CYP2C19 *2 or *3 had lower protection from recurrent TIAs or strokes." (PMID 32796505, 2020). "A recent meta-analysis of studies of patients prescribed clopidogrel for ischaemic stroke/TIA found CYP2C19 ROF carriers had an increased risk of recurrent stroke and MACE." (PMID 33198260, 2020). "There has been an increased focus recently on the impact of CYP2C19 ROF alleles in patients following a stroke." (PMID 33198260, 2020). "We recruited 131 patients with minor ischaemic stroke, within less than 7 days of stroke onset and a CYP2C19 loss-of-function allele, who had moderate-to-severe cerebral artery stenosis." (PMID 33121452, 2020). "We thus aim to conduct a meta-analysis to appraise evidence on the association of CYP2C19 genotype and clinical efficacy for stroke or TIA." (PMID 29901608, 2018). "At a clinical level, CYP2C19 allele carriers have major adverse cardiovascular events, including stroke." (PMID 22135769, 2011). "CYP2C19 gene polymorphism detection is recommended for patients who are available, and during treatment, the CYP2C19 genotype can be used to guide personalized precise medication use in patients with stroke." (PMID 38671468, 2024). "However, few studies have been conducted on the association between CYP2C19 gene polymorphisms and stroke." (PMID 38671468, 2024). "Similarly to the overall analysis, a significant association of CYP2C19 LOF alleles status was found with stroke in the subgroup of patients with European ancestry." (PMID 38038819, 2024). "CYP2C19 gene polymorphism significantly increase the risk of ischemic events such as stroke and MI." (PMID 39834800, 2024). "The CHANCE-2 trial demonstrated that compared to clopidogrel plus aspirin, the combination of ticagrelor and aspirin modestly lowered the risk of stroke at 90 days in patients with minor ischaemic stroke or TIA who were carriers of CYP2C19 loss-of-function alleles, but with more bleeding events." (PMID 37875703, 2024). "Taking this into consideration, we hypothesized that the common genetic variants of CYP2C19 could affect the dysregulation of adipocytokine levels and may have a possible role in the occurrence and recurrence of stroke in the Indian population." (PMID 37342754, 2023).
Stroke (continued). "Does CYP2C19 loss-of-function metabolizer status, which blunts metabolism of clopidogrel to its active form, modify the degree of benefit of ticagrelor-aspirin or clopidogrel-aspirin for patients with minor stroke or transient ischemic attack?" (PMID 37279000, 2023). "Compared with the white ethnic group, the Asian race is associated with a higher likelihood of CYP2C19 carriers, and hence clopidogrel might be less effective for secondary stroke prevention in Asian populations." (PMID 37580668, 2023). "CYP2C19 is a predominant determinant of patient responses to clopidogrel, a widely used antiplatelet drug in individuals at a higher risk of myocardial infarction or stroke." (PMID 37284308, 2023). "The current CHANCE-2 trial demonstrated that DAPT with aspirin and ticagrelor was superior to aspirin and clopidogrel in reducing the risk of subsequent stroke in Chinese patients with minor ischemic stroke or high-risk TIA who were carriers of CYP2C19 loss-of-function." (PMID 36744212, 2022). "Importantly, CYP2C19 loss-of-function alleles are associated with adverse cardiovascular events, including stent thrombosis, stroke, and myocardial infarction caused by reduced responsiveness to the antiplatelet drug clopidogrel." (PMID 35884507, 2022). "Our study mainly investigated the effect of CYP2C19 polymorphism on PD (high platelet reactivity or platelet reactivity level) and clinical outcomes (MACEs, MI, revascularization, stroke, definite stent thrombosis, and bleeding) for patients treated with ticagrelor." (PMID 35300607, 2022). "Whether adjusting the clopidogrel dose after CYP2C19 genotyping in stroke patients can reduce recurrent stroke risk needs further investigation." (PMID 33370282, 2020). "It has been shown that loss of function of CYP2C19 allele is time dependent; therefore, the adverse effects on stroke recovery may eventually wear off." (PMID 31359356, 2019). "Allelic frequency of CYP2C19 polymorphism among stroke patients." (PMID 28064328, 2017). "Genotypic Frequency of CYP2C19 polymorphism among stroke patients." (PMID 28064328, 2017). "The frequencies of CYP2C19 681AA (16.7% vs. 8.6%; P = 0.036), CYP2C19 636AA (7.0% vs. 2.2%; P = 0.038) genotype, CYP2C19 681A (36.4% vs. 27.6%; P = 0.023) and CYP2C19 636A (17.5% vs.10.3%; P = 0.010) allele in the recurrent stroke group are significantly higher than those in the first onset group." (PMID 25030528, 2014). "Patients with certain genetic variants in CYP2C19 have been found to have lower levels of the active metabolite, less platelet inhibition, and greater risk of major adverse cardiovascular events such as heart attack, stroke, and death." (PMID 20877456, 2010). "To conclude, CYP2C19 polymorphisms may play a significant role in the pathogenesis of stroke." (PMID 37342754, 2023). "This study aimed to describe allele, genotype, and phenotype frequencies for CYP2C19 and evaluate the effect of the CYP2C19 variants on treatment with ticagrelor-aspirin vs clopidogrel-aspirin in terms of prognosis for patients with minor stroke and high-risk TIA." (PMID 37279000, 2023). "CYP2C19 polymorphisms may play a significant role in the pathogenesis of stroke." (PMID 37342754, 2023). "Similarly, high on-treatment platelet reactivity (alternatively called resistance) in patients taking clopidogrel due to the presence of the CYP2C19 loss-of-function allele is associated with a failure for this antiplatelet to add to aspirin in preventing recurrence after minor stroke and TIA." (PMID 28630782, 2017). "Frequencies of CYP2C19 681AA (16.7% vs. 8.6%; P = 0.036), CYP2C19 636AA (7.0% vs. 2.2%; P = 0.038) genotype, CYP2C19 681A (36.4% vs. 27.6%; P = 0.023) and CYP2C19 636A (17.5% vs. 10.3%; P = 0.010) allele were significantly higher in recurrent stroke group than in the first onset group." (PMID 25030528, 2014).